STAT3 (signal transducer and activator of transcription 3)
Diseases named in the same sentence as STAT3 in open-access papers (continued):
Sharing a sentence is not in itself a finding about the gene and the disease.
tumor (continued). "In addition, we found that DHA inhibited STAT3 in peripheral blood immune cells and, more importantly, has the potential to counteract STAT3 activation by tumor cell-released factors in PBMCs and DCs, with no toxic effects." (PMID 28435516, 2017). "The Ca2+ binding S100 proteins, released from, for example, necrotic cells of the tumor mass, serve as DAMPs, alarmin molecules to the immune system; one member, the S100B molecule, promoted glioma growth by TAM chemoattraction through CCL2 upregulation and induction of STAT3." (PMID 28197019, 2017). "Moreover, miR-155 silencing results in increased levels of cleaved caspase-3 and SOCS1, which leads to STAT3 signaling suppression and tumor growth reduction in murine models of ALK negative ALCL." (PMID 28061468, 2017). "Stat3 showed an intense staining in tumor tissues compared to normal brain lacking Stat3 labeling." (PMID 28415725, 2017). "Thus, apart from activating these pathways in CSCs to promote tumor growth TAM-mediated STAT3 activation may also be necessary for EMT reprogramming in CSCs." (PMID 26980947, 2016). "In addition, Stat3 or Sox4 depletion in TICs reduced the tumour initiation and TIC ratios, while Stat3 or Sox4 knockdown in non-TICs had little effect on tumour initiation." (PMID 27553854, 2016). "Indeed, constitutively active STAT3 acts as a master regulator of cell metabolism, inducing aerobic glycolysis via HIF-1 α transcriptional induction as it is part of the complex signaling network that shapes the metabolic phenotype of tumour cells." (PMID 27769057, 2016). "STAT3 protein participates in diverse biological functions in normal and tumor cells." (PMID 27521216, 2016). "However, as STAT3 is also required for non-cancer cell function, any form of inhibition will not be specific to the tumor and will likely result in major side effects for the patient." (PMID 27148537, 2016). "This revealed unexpected roles for Stat3 in tumor development but not metastasis." (PMID 27589562, 2016). "Notably, we demonstrated that combined inhibition of PI3K and STAT3 with GDC-0032 and nifuroxazide in T-ALL cells as well as in xenograft tumor models of T-ALL resulted in maximal suppression of cellular proliferation and tumor progression in vivo." (PMID 27672444, 2016). "Two distinct response patterns upon STAT3 knockdown were observed: in two cell lines, STAT3 impairment resulted in enhanced STAT1 expression and reduced tumor growth; the other two cell lines displayed diminished STAT1 activity combined with accelerated xenograft tumor growth." (PMID 27191495, 2016). "Thus, tumours with low RAF1, high YAP1 expression contain larger clusters of nuclear STAT3." (PMID 28000790, 2016). "Another inhibitor of JAK1 and STAT3, a synthetic triterpenoid, bardoxolone methyl (C-28 methyl ester of 2-cyano-3,12-dioxooleana-1,9,-dien-28-oic acid, also known as CDDO-Me) abrogated the immune suppressive effect of MDSCs on CD8+ cytotoxic T-cells resulting in decreased tumor growth in mice." (PMID 27886105, 2016). "Expression of a dominant-negative STAT3 mutant in HSCs reversed the effects of tumor supernatants." (PMID 27148255, 2016). "However, RNAseq analysis of these tumor xenografts also uncovered modulation of many STAT1-regulated genes, including many, involved in radiation resistance, raising the possibility that C188-9 targeted STAT1, in addition to STAT3, in these tumors." (PMID 27027445, 2016). "In our study, S3I-201 could significantly reduce tumor cells in vitro and attenuate tumor burden in vivo without additional side effect through an on target effect by decreasing the level of p-STAT3." (PMID 26556875, 2015). "However, it remains unknown whether STAT3 signaling is involved in the acquisition of chemosensitivity and in enhancing EMT-related properties with tumor invasion in ATRT." (PMID 25638155, 2015).
tumor (continued). "We show that silvestrol induces direct anti-tumor activity against EBV-transformed lymphoblastoid cell lines (LCL), with growth inhibition, decreased expression of the EBV oncogene latent membrane protein-1, and inhibition of the downstream AKT, STAT1 and STAT3 signaling pathways." (PMID 25393910, 2015). "Therefore, STAT3 feed forward loops are established between tumor cells and non-transformed cells in the microenvironment, including immune cells." (PMID 26501341, 2015). "It is known that, in addition to STAT3, cytokines like IL-6 and IL-10, VEGF, and Oncostatin M are able to activate other pathways such as PI3K/AKT and Ras/MAPK that govern fundamental processes, such as cell proliferation, differentiation, metabolism, and tumor survival." (PMID 25695042, 2015). "Therefore, the inhibitory effect of CUEDC2 on NF-κB and JAK1/STAT3 is likely to prevent tumorigenesis, rather than promoting tumor growth." (PMID 26023733, 2015). "In addition to these “canonical” functions, it has become increasingly evident that STAT3 is also a regulator of cell energy metabolism, which can heavily impact on tumor transformation and growth." (PMID 26106584, 2015). "We postulate that ibuprofen may inhibit tumor cells also by COX- and lactate-independent mechanisms after long-term treatment in physiological dosages, whereas diclofenac mainly acts by inhibition of STAT-3 signaling and downstream modulation of glycolysis." (PMID 26485029, 2015). "Taken together, we found that miR-874 could inhibit tumor growth and angiogenesis in vivo, and that the negative correlation between miR-874 expression and STAT3 or VEGF-A levels." (PMID 25596740, 2015). "All above, our results revealed that blockade of STAT3 could target both non-CSCs to decrease tumor growth and CSCs to generate powerful treatment in the early stage of tumor." (PMID 26556875, 2015). "In the western blot data, both BM and the mixture of B16F10 tumor cells plus BM cells showed the activated STAT3 (pSTAT3), but it is not possible to determine whether the pSTAT3 expression is from the tumor cells or BM cells." (PMID 25889536, 2015). "Previous reports have demonstrated that STAT3 contributes to the hypoxia-induced enhancement of self-renewal in embryonic stem cells and other adult stem cells, as well as hypoxia-induced angiogenesis, hypoxia preconditioned human EPC-induced neovascularization, and tumor vasculature." (PMID 26219963, 2015). "Like TNF-α, IL-6 facilitates tumor development by promoting the conversion of non-cancer cells into tumor stem cells in low-attachment culture conditions by up-regulating Oct 4 gene expression through activating the IL-6R/JAK/STAT3 signaling pathway." (PMID 26418748, 2015). "IHC analysis revealed absence of pY-Stat3 and Stat3 expression in Ptenpc−/−IL-6−/− tumours." (PMID 26198641, 2015). "Additionally, tumor biology unaccounted for in this experience may also impact survival, such as the presence of radioresistant biomarkers like SYK, STAT3, and SKY pathway genes." (PMID 26029663, 2015). "The JAK/STAT3 and ERK signaling pathways are important pathways in cell growth and apoptosis and the inactivity of these pathways may regulate the Bcl2 family resulting in growth arrest and apoptosis in certain tumor cells." (PMID 25373392, 2015). "Once binding to IL-6 receptor (IL-6R) and gp130 receptor, IL-6 could activate STAT3, mitogen-activated protein kinase (MAPK) and phosphatidylinositol 3-kinase (PI3K) pathways and increase tumor metastasis, indicating that IL-6 increasing metastasis is IL-6R/gp130 dependent." (PMID 26528698, 2015).
tumor (continued). "In this context, it has been hypothesized that the activation of STAT-3 may be due to kinases that cannot be suppressed by SOCS-3 or that tumor cells may develop strategies to bypass the negative regulation mediated by SOCS-3." (PMID 24883303, 2014). "In the absence of STAT3 tumor surveillance is significantly impaired." (PMID 24473086, 2014). "Furthermore, CA treatment appeared to inhibit STAT3 activation in splenic MDSCs in the tumor-bearing mice (data not shown)." (PMID 24738052, 2014). "Our murine model and in vitro studies confirm that in addition to the direct suppression of T cells, Mo-MDSC also play an important role in promoting tumor stemness and EMT in a STAT3-dependent manner and this effect is independent of any other cell type in the tumor." (PMID 24652403, 2014). "The role of STAT3 in tumor suppression by regulation of JunB has not been made clear but this is an example of a STAT3-regulated gene that may support or suppress tumor growth." (PMID 24743777, 2014). "Furthermore, as was observed in the prophylactic model, ablation of STAT3 in DCs did not enhance the therapeutic anti-tumor responses elicited by WT DCs." (PMID 24806510, 2014). "Importantly, recombinant LIF could activate STAT3 and downregulate RET and induce tumor suppression in human MTC cells xenografted in mice, suggesting its potential as a therapeutic reagent to treat MTC." (PMID 24662939, 2014). "However, the fact that UA abrogates STAT3 activation suggests that UA impairs tumor development not only due to its direct cytotoxicity to tumor cells but also by inhibiting the protumoral functions of TAMs and MDSCs." (PMID 24738052, 2014). "We did not observe significant differences in total STAT3 and NFκB protein expression among tumor cells either in vitro or in vivo, except for the low NFκB expression in HeLa cells in vivo (a longer exposed autoradiogram shows a band correspondent to NFκB in HeLa cells)." (PMID 25400927, 2014). "Finally, in spite of cytokine secretion by tumor cells, leukocytes infiltrating SiHa and HeLa tumors displayed almost negligible STAT3 and no NFκB phosphorylation." (PMID 25400927, 2014). "Immunohistochemical staining showed that STAT3, p-STAT3 and its downstream genes c-Myc, cyclinD1, survivin and VEGF could be detected in either cytoplasm or the nuclei of tumor tissues in NaCl control group but became apparently reduced in resveratrol-treated tumors." (PMID 24587049, 2014). "Therefore, persistent STAT3 activation in many cancers can establish a feed-forward loop between the tumor and the non-transformed stroma cells such as myeloid-derived suppressor cells, cancer-associated fibroblasts, and adipocytes." (PMID 24662939, 2014). "IL-1β released by stromal cells together with other tumor-derived factors, including granulocyte macrophage colony-stimulating factor (GM-CSF), cyclooxygenase 2 (COX-2), IL-6, and VEGF, induce the accumulation and expansion of MDSCs by triggering Janus kinase (JAK)/STAT3 pathways." (PMID 25136593, 2014). "Furthermore, no significant tumor suppressor effect of STAT3 was observed in the presence of normal PTEN expression." (PMID 24995504, 2014). "It is currently unclear whether this non-canonical STAT3 function is also important to mediate tumor suppression of MTC cells." (PMID 24662939, 2014). "The significant overlap between tumor prosurvival and proliferative genes activated by STAT3 and NF-κβ, is not surprising based on data showing that STAT3 maintains the acetylation and nuclear retention of the NF-ΚΒ transcriptional subunit RelA in Du145 PCa cells as well as hematopoietic cells." (PMID 24722453, 2014). "IL-28 secreted by MDSCs stimulates STAT3 in tumor cells, which results in increased expression of angiogenic factors and subsequent induction of angiogenesis by endothelial cells, epithelial-mesenchymal transition (EMT) and increased migration of tumor cells in vitro." (PMID 25075523, 2014).
tumor (continued). "STAT3 activation in immature dendritic cells has been shown to impair the expression of MHC class II molecules, CD80, CD86 and IL-12, thereby hindering their maturation and thus decreasing their ability to promote the anti-tumor function of CD8-positive T cells and natural killer cells." (PMID 24995504, 2014). "Thus, STAT3 displays both pro- and anti-metastatic effects in CRC, the outcome of which may be determined by the tumor microenvironment." (PMID 24995503, 2014). "However, the effect of endothelial cell-secreted IL-6 on tumor cell STAT3 and overall tumor growth is not known." (PMID 24533454, 2014). "Thus, multi-modality therapy involving cancer vaccines may be the key to the role of STAT3 inhibition in curative immunotherapy by promoting CD4 and CD8 T cell mediated tumor-specific killing." (PMID 24518612, 2014). "Moreover, K5.STAT3C transgenic mice expressing constructively active STAT3, form tumor faster and a much greater number than do their nontransgenic counterpart." (PMID 24743778, 2014). "Subsequently, the authors combined RNAi against STAT3 and ErbB2 with irradiation in an U251 xenograft mouse model, which led to a highly significant inhibition of tumor growth compared to single RNAi treatment without toxic effects in normal astrocytes from the brain of Wistar rats." (PMID 25268165, 2014). "However, iNOS and NO also have potential tumor suppressing functions and the role of STAT3 in these have not been clearly addressed." (PMID 24743777, 2014). "Thus, we hypothesized that IMQ-induced ROS activate both the STAT3 and PI3K/Akt pathways to promote HIF-1α expression but do not increase the stability or inhibit the proteasomal degradation of HIF-1α in tumor cells." (PMID 24658058, 2014). "It has been reported that STAT3 is also involved in expansion of MDSCs, activation of CD14+HLA-DRnegative/low MDSCs in blood of cancer patients, expression of immunosuppressive arginase-1 in human MDSCs, survival of Tregs, and anti-tumor activity of CD8+ T cells." (PMID 23755373, 2013). "Furthermore, the loss of intratumoral NF-κB p65 did not further enhance inhibition of global STAT3 activation, or reduce tumor growth as mediated by AZD1480, which we observed previously." (PMID 24244348, 2013). "In particular, it was recently reported that WP1066, a STAT3 inhibitor, reduced RCC tumor growth and metastasis, but whether this inhibitor required STAT3 for its anti-tumor effects was not directly assessed." (PMID 24324713, 2013). "The primary mechanism for activation of Stat3 in mouse keratinocytes exposed to tumor promoters is through activation of epidermal growth factor receptor (EGFR), although other pathways may also contribute to its activation during tumor promotion." (PMID 23577258, 2013). "Reports suggest that the tumor cells lacking STAT3 activation could efficiently produce the proinflammatory factors that promote the maturation and antigen presenting ability of dendritic cells." (PMID 24199193, 2013). "However, knock-down of STAT-3 did not abrogate IL-24 protein-mediated killing of the receptor-positive tumor cells indicating STAT-3 activation was not required for tumor cell killing." (PMID 24377906, 2013). "In view of the effective action of berberine to inhibit STAT3 and relatively low toxicity, berberine may serve as an effective chemopreventive agent or conjugant medicine for treatment of NPC through modulating the inflammatory tumor microenvironment." (PMID 24380387, 2013). "Nguyen and coworkers observed that activation of STAT3 signaling in tumor cells or in inflammatory immune cells modulates secretion of various inflammatory factors such as IL6 and TNFα that act as an immunosuppressors, and increase the probability of survival of tumor cells." (PMID 24199193, 2013).
tumor (continued). "Western analysis on tumour lysates showed that NVP-AST487 treatment alone, or combined with fulvestrant or tamoxifen caused a significant decrease in the pY705-Stat3/Stat3 ratio compared to controls; neither of the endocrine agents alone affected pY705Stat3 levels." (PMID 23868506, 2013). "However, B cell Stat3 was not essential for the proliferative potential of B cells in the tumor milieu (right)." (PMID 23734190, 2013). "Since QPCR analysis showed more than 3-fold induction of AP2 expression by TGFβ within responsive low grade tumor cells, whereas only marginal to no change was detected in STAT3, and STAT1 transcript levels (data not shown), thus further analysis of AP2 binding was prioritized." (PMID 23840623, 2013). "While myeloid cells and their intrinsic Stat3 signaling have been demonstrated to be important for tumor progression via multiple mechanisms, including angiogenesis, the counterpart effects of Stat3 ablation in B cells on tumor have not been assessed." (PMID 23734190, 2013). "Interestingly, elevated STAT3 activity can increase HIF-1α promoter activity in both cancer cells and nontransformed, tumor-associated myeloid cells in the TME." (PMID 24314323, 2013). "Our study provides strong evidence of the anti-tumor growth potency of JAK inhibitor AZD1480 in pediatric solid tumors, providing proof-of principle that inhibition of the JAK/STAT3 signal transduction could be a promising therapeutic target for high-risk pediatric solid tumors." (PMID 23531921, 2013). "After activated via phosphorylation, STAT3 modulates the expression of key genes involved in the regulation of cell apoptosis, proliferation and angiogenesis; we therefore examined the effect of EESP on STAT3 phosphoralytion level (pSTAT3) using IHS assay in tumor tissues." (PMID 23800091, 2013). "In contrast, sorafenib analogues SC-1 and SC-43, with enhanced p-STAT3 inhibition in comparison with sorafenib, that is, enhanced SHP-1 activity, resulted in more potent apoptotic activity and afforded better protection against xenograft tumor growth than sorafenib." (PMID 23938089, 2013). "Consistently, the expression of PIAS3 was significantly low in TRAMP-C1 siAR tumours, confirming that PIAS3 is an AR downstream target, and the PIAS3 down-regulation by AR silencing could be an important step for STAT3 activation in PCa cells." (PMID 23982944, 2013). "In addition, the transcription factor, STAT3, as well as the immunosuppressive cytokine, TGF-β, are abundant in the tumor microenvironment and can also contribute to maintaining elevated IDO expression in DC or tumor cells." (PMID 23898333, 2013). "Conversely, targeting STAT3 activation inhibits tumor growth and metastasis both in vitro and in vivo without affecting normal cells, thus suggesting that STAT3 could be a valid molecular target for cancer therapy." (PMID 24199193, 2013). "STAT3 is constitutively active in most tumor cells but not in normal cells." (PMID 22619672, 2012). "However, AZD1480 repressed the growth of STAT3- deficient TPC-1 cells in vitro and in vivo, demonstrating that its effects in this cell line were independent of STAT3 in the tumor cells." (PMID 23056499, 2012). "A new hairpin decoy oligonucleotide (hpdODN) carrying STAT3's DNA binding consensus sequence was designed following 3D analysis of protein/DNA interaction and shown to induce the death of STAT3-dependent tumor cells without interfering with STAT1, a key effector of cell death." (PMID 22423663, 2012). "In conclusion, inhibition of Stat3 by a novel, selective small molecule decreased the candidate TIC subpopulation in human cancers transplanted in mice, resulting in not only a decrease in tumor volume, but also prolongation of the time to tumor recurrence significantly." (PMID 22879872, 2012). "Importantly, structural changes in the compound improved its in vitro solubility profile, but did not compromise anti-tumor potency or STAT3 specificity." (PMID 22899991, 2012).